MUC1 (mucin 1, cell surface associated)
Diseases named in the same sentence as MUC1 in open-access papers (continued):
Sharing a sentence is not in itself a finding about the gene and the disease.
gout (11 papers, 2020 to 2025). A condition characterized by painful swelling of the joints, which is caused by deposition of urate crystals. "Accordingly, rs12411216 and rs4072037 at the MUC1 locus have been shown to be associated with blood urate levels and gout in several GWAS in the East Asian population." (PMID 38406838, 2024). "In conclusion, our data demonstrated the pleiotropic effects of MUC1 variants with novel associations for gout, red blood cell parameters, and MUC1 DNA methylation." (PMID 34638981, 2021). "The results revealed that gout and microalbuminuria were significantly associated with MUC1 gene variants." (PMID 34638981, 2021). "Furthermore, we identified novel genome-wide significant associations between MUC1 functional SNPs and gout, red blood cell parameters (hematocrit, hemoglobin, and red blood cell counts), and MUC1 gene-body DNA methylation." (PMID 34638981, 2021). "Three LD blocks existed in chromosome 1 for the variants relating to gout, which were composed of genes DNAJC16, AGMAT (first block), PDZK1, CD160, NUDT17 (second block), TRIM46, MUC1, MTX1, and ASH1L (third block)." (PMID 36221101, 2022). "Our data, thus, imply that allele T of rs2075571 leads to decreased serum urate levels via an increased expression of MUC1 in the corpus mucosa, which might have protective effects against gout." (PMID 38406838, 2024). "Moreover, rs9286836 (NUDT17) and rs4971100 (TRIM46), rs4072037 (MUC1) and rs2974935 (MTX1) also revealed significant associations with gout (all p-values <1e−8)." (PMID 36221101, 2022). "Surprisingly, variants on chromosome 1, such as rs7546668 (DNAJC16), rs10927807 (AGMAT), rs9286836 (NUDT17), rs4971100 (TRIM46), rs4072037 (MUC1), and rs2974935 (MTX1), showed significant associations with gout in both discovery and replication cohorts (all p-values < 1e−8)." (PMID 36221101, 2022). "All these findings suggest the importance of MUC1 in the development of hyperuricemia and gout." (PMID 34638981, 2021). "This study performed a GWAS in a large sample size and found genes DNAJC16, AGMAT, NUDT17, TRIM46 MUC1, and MTX1 on chromosome 1 relating to gout disease." (PMID 36221101, 2022). "Surprisingly, variants on chromosome 1 located in genes DNAJC16, AGMAT, NUDT17, TRIM46, MUC1 and MTX1 showed significant associations with gout, which finding had not been reported before." (PMID 36221101, 2022).
head and neck squamous cell carcinoma (11 papers, 2006 to 2024). A squamous cell carcinoma that arises from any of the following anatomic sites: lip and oral cavity, nasal cavity, paranasal sinuses, pharynx, larynx, and salivary glands. "Mucin 1 (MUC1), a transmembrane glycoprotein, has shown to be as the possible prognostic marker to predict the risk of aggressive head and neck squamous cell carcinoma (HNSCC)." (PMID 32662743, 2020). "Glycoproteins such as EGFR, E-cadherin, CD44, PD-1/PD-L1, B7-H3 and Muc1 play important roles in the progression of head and neck squamous cell carcinoma (HNSCC), and their levels of glycosylation and changes in glycosyl structure are closely linked to HNSCC progression and malignant transformation." (PMID 33531990, 2021). "In a preclinical model of head and neck squamous cell carcinoma (HNSCC), MUC1-CAR-T cells specifically killed MUC1+ HNSCC cell lines in vitro and secreted IL-2, interferon γ (IFN-γ), and TNF-α." (PMID 38727261, 2024). "Identified the expression of MUC1 is higher in head and neck squamous cell carcinomas than non‐neoplastic tissues." (PMID 31800160, 2020).
intrahepatic cholangiocarcinoma (11 papers, 2006 to 2025). A carcinoma that arises from the intrahepatic bile duct epithelium in any site of the intrahepatic biliary tree. "For example, MUC1 stabilizes β-catenin and promotes nuclear translocation to active Wnt genes that drive the proliferation, invasion, and metastasis of intrahepatic cholangiocarcinoma." (PMID 40699805, 2025). "MUC1 apomucin is frequently expressed in various subtypes of intrahepatic cholangiocarcinoma, including mass-forming and periductal infiltrating forms." (PMID 27933122, 2009). "A recent study has reported the use of Tn-MUC1-targeted CAR T cells in intrahepatic cholangiocarcinoma (ICC)." (PMID 38473878, 2024). "The Tn-MUC1 targeted CAR-T cells also showed effectiveness in targeting and eliminating Tn-MUC1-positive intrahepatic cholangiocarcinoma in both in vivo and in vitro models." (PMID 40699805, 2025). "MUC1 and MUC4 have been reported as being independent diagnosis and prognostic markers for predicting poor outcomes in patients with mass-forming intrahepatic cholangiocarcinoma." (PMID 27933122, 2009). "In intrahepatic cholangiocarcinoma (ICC), the upregulation of myeloid leukemia factor 1 (MLF1) is significantly correlated with the upregulation of MUC1 expression involving the EMT of cancer progression." (PMID 40699805, 2025).
Sjögren’s syndrome (11 papers, 2010 to 2025). "MAM expression and MUC1 immunoreactivity in the conjunctiva were reduced in patients with Sjögren’s syndrome (SS)." (PMID 37106448, 2023). "In humans, MUC1 expression is increased in allergic keratoconjunctivitis and Sjögren's syndrome but decreased in DED." (PMID 31552195, 2019). "In this study of MUC1 in dry eye disease, we characterize the expression of MUC1 in Sjogren’s syndrome dry eye as compared with aqueous deficient (KCS) dry eye and non dry-eyed (NDE) controls, to gain further insight into the role that MUC1 may play in dry eye disease." (PMID 20806091, 2010). "Key words:Primary Sjögren's syndrome, mucin, MUC7, MUC5B, MUC1, sulphate oligosaccharides." (PMID 33247578, 2021). "It is a common opinion that Primary Sjögren Syndrome (pSS) damages the exocrine glands and determines the reduction of secreted saliva, some studies show that there are qualitative anomalies of the mucins produced in saliva, including MUC7, MUC5B, MUC1." (PMID 33247578, 2021).
chronic obstructive pulmonary disease (10 papers, 2011 to 2026). A chronic and progressive lung disorder characterized by the loss of elasticity of the bronchial tree and the air sacs, destruction of the air sacs wall, thickening of the bronchial wall, and mucous accumulation in the bronchial tree. "Sputum taken from patients suffering from chronic obstructive pulmonary disease (COPD) also contains significantly more MUC1 compared to samples taken from individuals with prolonged coughing." (PMID 31069176, 2019). "MUC1 levels in sputum were increased in adults with chronic obstructive pulmonary disease." (PMID 29186029, 2017).
colorectal adenocarcinoma (10 papers, 2006 to 2025). The most common type of colorectal carcinoma. "The results proved that the MUC1 peptide vaccine induced an immune response in newly diagnosed colorectal adenocarcinoma patients, with an absolute reduction rate of adenoma recurrence of 38% compared to the placebo." (PMID 39861694, 2025). "Further investigations to characterise the in vivo effects and potential value of [177Lu]Lu-DOTA-C595 in other MUC1-CE expressing malignancies such as lung, ovarian and colorectal adenocarcinoma are warranted." (PMID 37578571, 2023).
infertile (10 papers, 2012 to 2025). "Considering the increase of MUC-1 expression in response to progesterone and also the relationship of shorter MUC-1 alleles with infertility, the anti adhesive role of MUC-1 in human becomes controversial." (PMID 24551783, 2013). "Several studies indicated that smaller alleles of MUC-1 show a higher frequency in women with infertility due to embryo implantation failure when compared to patients with no history of infertility." (PMID 24551783, 2013). "Previous studies showed that fertile women exhibited a higher level of endometrium MUC-1 expression than infertile patients." (PMID 35646061, 2022). "MUC1 can be decorated with sialyl-Lewis X in endometrial cells and expression of MUC1 in the infertile endometrium is significantly different than in fertile endometrium." (PMID 33596915, 2021). "The precise expression levels and role of CFTR, MUC1 and NF KappaB during the implantation window in infertile patients with hydrosalpinx remain to be explored." (PMID 23061681, 2012). "Increased NF KappaB expression and decreased CFTR and MUC1 expression in the endometrium of infertile patients with hydrosalpinx reinforce the involvement of a molecular mechanism in the regulation of endometrial receptivity." (PMID 23061681, 2012). "In this study, we observed that MUC1 was significantly downregulated in the endometrium of infertile patients with hydrosalpinx." (PMID 23061681, 2012). "This study demonstrates that the expression of NF KappaB is significantly increased, while the expression of CFTR and MUC1 are significantly decreased in the endometrium of infertile patients with hydrosalpinx." (PMID 23061681, 2012). "Because of the importance of proper expression of Muc1, itsaberrant expression may affect uterine receptivity and lead to implantation failure andsubsequent infertility." (PMID 33098389, 2020). "Low levels of MUC1 could damage the embryo selection function of the endometrium in infertile patients with hydrosalpinx, thus increasing the miscarriage rate or reducing the implantation rate." (PMID 23061681, 2012). "Moreover, MMP‐9 depletion and MUC1 overexpression may be considered as part of a complicated pathway leading to infertility and to the progression of carcinogenesis." (PMID 28244681, 2017). "Therefore, we examined the expression of CFTR, NF KappaB and MUC1 in endometrial tissues collected from infertile patients with or without hydrosalpinx, and analyzed the relationship between CFTR and NF KappaB or MUC1 expression in the endometrium tissues of infertile patients with hydrosalpinges." (PMID 23061681, 2012). "The endometrium of infertile patients with hydrosalpinx had significantly higher NF KappaB mRNA and protein expression, and significantly lower CFTR and MUC1 mRNA and protein expression, compared to control infertile patients." (PMID 23061681, 2012). "Since pregnancy was achieved for some of the infertile women, this does posit that an uncharacterized alternative mechanism could promote implantation and pregnancy under certain HOXA10 and MUC1 expression conditions." (PMID 28830391, 2017). "Spearman’s correlation analysis demonstrated that a positive correlation existed between the expression of CFTR and MUC1 mRNA in the entire cohort of infertile patients with and without hydrosalpinx (r = 0.65, P < 0.05)." (PMID 23061681, 2012). "Interestingly, we observed a positive correlation between CFTR and MUC1 mRNA and a negative correlation between CFTR and NF KappaB mRNA in the endometrium of infertile women." (PMID 23061681, 2012).
influenza (10 papers, 2019 to 2025). An acute viral infection of the respiratory tract, occurring in isolated cases, in epidemics, or in pandemics; it is caused by serologically different strains of viruses (influenzaviruses) designated A, B, and C, has a 3-day incubation period, and usually lasts for 3 to 10 days. "Among these cell surface mucins, MUC1 is implicated in the pathogenesis of influenza infection." (PMID 31307416, 2019). "The phase I trial NCT02544880 recently completed, where Hiltonol and Mucin1 were combined to make the MUC1 vaccine; together with influenza vaccine and PDE5 inhibitor Tadalafil, MUC1 vaccine has been used to treat solid tumors." (PMID 36479129, 2022). "This is also the first study that we are aware of that provides quantitative estimates of the in vivo effects of cs-mucin MUC1 on influenza infection." (PMID 34066999, 2021). "We analyze the data with two mathematical models of influenza viral dynamics under a Bayesian framework, quantifying the potential effects of cs-mucin MUC1 in influenza infection." (PMID 34066999, 2021). "Response to vaccines was evaluated by ELISA on the serum to determine the concentration of IgM, IgG, and IgA against the MUC1 or the influenza antigens." (PMID 31214178, 2019). "This study improves our understanding of the dynamic role of MUC1 against influenza infection and may support the development of novel antiviral treatments and immunomodulators that target MUC1." (PMID 34066999, 2021).
intraductal papillary mucinous neoplasm (10 papers, 2012 to 2025). "We also reported that individuals with pancreatic premalignancy, Intraductal Papillary Mucinous Neoplasm (IPMN), had increased circulating levels of MDSC that inversely correlated with spontaneous antibody responses against the pancreatic tumor associated antigen MUC1, abnormally expressed on IPMN." (PMID 31275327, 2019). "It was shown that the intestinal subtype of IPNB was more frequently positive for MUC1 and less frequently positive for MUC2, MUC5AC and CDX2 (a MUC2 regulating transcription factor), compared to each subtype of pancreatic IPMN." (PMID 30875782, 2019). "Some have reported that expression of MUC1 and MUC4 increases with increasing pancreatic intraepithelial neoplasia (PanIN) and/or intraductal papillary mucinous neoplasm (IPMN) grade." (PMID 27283771, 2016). "In another study, analysis of EVs using a digital extracellular vesicle screening technique (DEST) reported the presence of a panel of mucins, including MUC1, MUC2, MUC4, MUC5AC, MUC6, and MUC13, in a cohort of 133 patients harboring intraductal papillary mucinous neoplasms (IPMN)." (PMID 36980526, 2023). "We selected MUC1, MUC2, and MUC5AC for further investigation because they were routinely stained in the postoperative pathological reports of FUSCC for antidiastole and grading of intraductal papillary mucinous neoplasms." (PMID 35910854, 2022). "A previous study showed that analysis of DNA methylation status in promoters of MUC1, MUC2 and MUC4 (MSE analysis of pancreatic juice samples) could distinguish between gastric type intraductal papillary mucinous neoplasm (IPMN), intestinal type IPMN, other type IPMN and PDAC." (PMID 27283771, 2016).
bladder tumors (9 papers, 2015 to 2025). "MUC1 was overexpressed in ovarian, breast, colon, pancreas, and bladder tumors and was often associated with the epithelial-mesenchymal transition of different cancer cells, being considered an important metastasis gene." (PMID 34149728, 2021). "Sialyl-Tn expression was also associated with the mucin glycoproteins MUC1, MUC2, and mucin antigen of the urinary bladder (MAUB) derived from bladder tumors." (PMID 32075174, 2020). "In this study, MUC1 was found to express Core-2 extended polylactosamine glycans, primarily in C2GnT-expressing bladder tumors." (PMID 32075174, 2020). "Subsequently, MUC1− and CD44v6+ cells were isolated, and a slightly increased clonogenicity was observed for these cells compared with unsorted bladder tumour cells." (PMID 29207682, 2017). "In an immunohistochemistry study of 539 bladder tumours MUC1 was expressed in 62% of the tumours and increased with tumour grade." (PMID 28248271, 2015). "Interestingly, the tolerogenic effect of short-chained O-glycans has also been correlated with bladder tumour metastasis through a mechanism in which MUC1 carrying core 2 O-glycans functions as a molecular shield against NK cells attack, thereby promoting metastization." (PMID 29207682, 2017).
colonic adenomas (9 papers, 2016 to 2025). "Collectively, our findings could provide an explanation for observations that patients diagnosed with premalignant advanced colonic adenomas who have elevated circulating MDSC failed to produce antibodies in response to vaccination with the MUC-1 tumor-associated antigen." (PMID 27929373, 2016). "MUC1 expression has been reported in human colon adenoma and adenocarcinoma, but not in normal colonic epithelia." (PMID 36980805, 2023). "Patients with advanced colon adenoma were vaccinated with MUC1 to assess the ability of this vaccine to induce an anti-MUC1 immune response and long-term memory without toxicity." (PMID 36612133, 2022). "A study evaluated the immunogenicity of a vaccine based on MUC1 in patients without CRC cancer but with advanced colonic adenomas (precursors of CRC) and showed high levels of anti-MUC1 IgG along with long-lasting immune memory in 44% of these individuals." (PMID 32210966, 2020).
dry eye (9 papers, 2010 to 2024). "MUC1 is a cell-associated mucin that has been studied in dry eye patients." (PMID 35205178, 2022). "We propose that the conjunctival epithelium of Sjogren’s subjects reacts to dry eye changes in the tear film that cause increased shedding of MUC1 and increased production of this molecule in an attempt to protect the ocular surface and to maintain a healthy surface phenotype." (PMID 20806091, 2010). "In vitro, inflammatory mediators that have been found in the tear film of dry eye patients have been shown to increase MUC1 expression in a human limbal corneal epithelial cell line." (PMID 20806091, 2010). "An isoform of MUC1, called MUC1/A, has a lower expression in dry eye patients." (PMID 35205178, 2022). "SNPs in the MUC1 gene have been identified in SS and dry eye subjects." (PMID 34349764, 2021). "Especially, reduction of MUC1 expression in dry eye local tissue is reportedly most prominent and could be a marker for diagnosis or evaluation of the disease severity." (PMID 26818460, 2015). "Expressions of MUC1, MUC2, MUC4, and MUC5AC are significantly lower in conjunctival epithelium gathered by impression cytology in the patients with dry eye syndrome compared with that in normal subject." (PMID 26818460, 2015). "In this study, we explored the relationship between the quantity of MUC1 and MUC16 protein and mRNA with dry eye symptoms and tear stability in a cohort of PMW that were recruited without bias of specific inclusion criteria." (PMID 23687433, 2013). "Our findings would suggest that this compensatory or protective mechanism is most prevalent in SS dry eye disease, but may be related to disease severity, as suggested by the increased soluble MUC1 seen in KCS subjects over NDE subjects in our results." (PMID 20806091, 2010). "In addition, reduced mucin production protein (MUC1), suggests that our DED organoid model can reflect functional dry eye characteristics." (PMID 38961590, 2024). "In this study, PMW with a history of dry eye displayed significantly increased membrane-bound MUC1 and MUC16 protein and MUC1 mRNA levels compared to asymptomatic controls, prompting the hypothesis that increased mucin concentration may be a compensatory response to irritation." (PMID 23687433, 2013).